GPM6A (glycoprotein M6A)
Diseases named in the same sentence as GPM6A in open-access papers (continued):
Sharing a sentence is not in itself a finding about the gene and the disease.
liver cancer (2 papers, 2021 to 2025). An epithelial or non-epithelial malignant neoplasm that arises from the liver. "Overexpression of GPM6A decreases the proliferation of liver cancer cells, colony formation, invasion, and migration, inhibits the carcinogenic function of microRNA‐96, and can also induce apoptosis of HCC cells." (PMID 39957375, 2025). "In GPM6A‐overexpressed liver cancer cells, the function of oncogenic microRNA‐96 was significantly inhibited." (PMID 39957375, 2025). "There are data suggesting that GPM6A inhibits liver cancer cells through the Smad signaling pathway, but the function of GPM6A still needs to be validated in vivo." (PMID 39957375, 2025). "The silencing of circCCNB1 promotes the cloning ability, G1‐S cell cycle transition, and xenograft tumor growth of liver cancer cells by downregulating GPM6A." (PMID 39957375, 2025). "Although there is data indicating that GPM6A inhibits liver cancer cells through the Smad pathway, its function needs to be validated in vivo." (PMID 39957375, 2025). "GPM6A overexpression hinders cell proliferation, formation of colony, as well as migration and invasion of some types of liver cancer cells." (PMID 39957375, 2025). "We report for the first time that LOC644135, ELN, GULP1, ENSG00000248635, GPM6A, and PI15 are associated with the risk of liver cancer recurrence." (PMID 34956309, 2021). "The interaction between GPM6A and microRNA‐96 in liver cancer requires additional validation." (PMID 39957375, 2025).
lymphoid leukemia (2 papers, 2022 to 2025). A malignant lymphocytic neoplasm of B-cell or T-cell lineage involving primarily the bone marrow and the peripheral blood. "In lymphoid leukemias, GPM6A and GPM6B are overexpressed and act as oncogenes in the development of these malignancies." (PMID 35883571, 2022). "GPM6A is a highly expressed potential oncogene in lymphoid leukemia." (PMID 39957375, 2025).
brain tumors (1 paper, 2023). "For example, similar expression levels of NDRG1, LDHA, MHCII molecules, interferon genes, GPM6A, C9, and SRGAP2 were discovered in different myeloid subpopulations, indicating the similar functional states in different brain tumors." (PMID 38094301, 2023).
chronic lymphocytic leukemia (1 paper, 2025). "Human GPM6A is specifically overexpressed in chronic lymphocytic leukemia (CLL) and mantel cell lymphoma (MCL)." (PMID 39957375, 2025).
colon cancer (1 paper, 2025). "Decreased expression of GPM6A protein was found in highly differentiated CRC tissues, while higher expression levels were observed in minimally differentiated or undifferentiated colon cancer tissues, but its relationship with CRC is still unclear." (PMID 39957375, 2025).
diabetes (1 paper, 2023). "While diabetes has been linked to aberrant calcium signaling, GPM6A and CHRNA9 have not previously been specifically implicated in contributing to CVD risk in diabetes." (PMID 37533055, 2023).
learning disability (1 paper, 2018). A group of disorders that affect a person's ability to learn or process specific types of information which is in contrast to his/her apparent level of intellect. "On the other hand, de novo duplication of GPM6A gene leading to the higher expression of GPM6A has been connected to learning disability and anomalies in the behavior suggesting the importance of accurate expression of GPM6A for cognitive function." (PMID 30233315, 2018).
Leukoencephalopathy (1 paper, 2010). This term describes abnormality of the white matter of the cerebrum resulting from damage to the myelin sheaths of nerve cells. "Downregulated genes included amyloid beta precursor protein‐binding, family a member 2 (APBA2); glycoprotein m6a (GPM6A); megalencephalic leukoencephalopathy with subcortical cysts 1 (MLC1); ankyrin repeat and btb domain containing 2 (ABTB2); and ring finger protein 43 (RNF43)." (PMID 19793339, 2010).
liver fibrosis (1 paper, 2022). "In addition, GPM6A has also been used as a cell marker to distinguish hepatic stellate cells and mesenchymal cells and was significantly correlated with liver fibrosis." (PMID 35002514, 2022).
narcolepsy (1 paper, 2020). A sleep disorder characterized by a tendency for excessive sleepiness during the day which occurs even after adequate sleep in the nighttime. "Located within the gene, the functions PPP2R2C, GPM6A, EPHX2, NKAIN3, ZNF365, TENM4, and PR2Y11 are related to narcolepsy." (PMID 32358372, 2020).
neuroblastoma (1 paper, 2018). Neuroblastoma (NB) is the most common solid, extracranial childhood tumor. "Here, we demonstrate that the C- but not the N-terminal cytosolic end of Gpm6a is required for the formation of filopodia by Gpm6a in cultured neurons from rat hippocampus and in neuroblastoma cells N2a." (PMID 30233315, 2018).
pancreatic cancer (1 paper, 2009). "Knock down of VAV3 and GPM6A in pancreatic cancer cell lines desensitized the cells to gemcitabine and AraC." (PMID 19898621, 2009).
retinal diseases (1 paper, 2004). "In many instances, this results in a significant reduction of genes in the respective intervals offering a manageable number of candidates for retinal diseases (e.g. the RP29 locus contains 28 SGPs of which 5 are present in the reference retinome including GPM6A, WDR17, FLJ22649, VEGFC, AGA)." (PMID 15283859, 2004).
thyroid cancer (1 paper, 2025). "Apart from that, GPM6A is a new associated protein in thyroid cancer, and its expression level in thyroid cancer is significantly lower than that in normal tissues." (PMID 39957375, 2025). "Compared with normal tissue, GPM6A expression in thyroid cancer was significantly lower." (PMID 39957375, 2025). "GPM6A expression in thyroid cancer is significantly lower than that in normal tissues." (PMID 39957375, 2025).
Tinnitus (1 paper, 2022). Tinnitus is an auditory perception that can be described as the experience of sound, in the ear or in the head, in the absence of external acoustic stimulation. "A SNP close to GPM6A achieved genome-wide significance, and 19 independent genetic loci showed suggestive association with tinnitus." (PMID 36581688, 2022). "The genomic region close to GPM6A associated with tinnitus revealed a suggestive association with tinnitus-related distress." (PMID 36581688, 2022). "A genomic region containing SNP (rs71595470) near GPM6A revealed a significant association with tinnitus, and 19 SNPs showed suggestive associations with tinnitus." (PMID 36581688, 2022). "Together with the GWAS signals upregulated in the hippocampus, our results suggest that inefficient regulation of the genomic region associated with tinnitus involving GPM6A in the hippocampal neurons could influence tinnitus perception." (PMID 36581688, 2022). "The genomic region containing a lead SNP in the vicinity of GPM6A might lie at the crossroad between tinnitus and psychiatric comorbidities." (PMID 36581688, 2022).
type 1 diabetes (1 paper, 2023). "Importantly, our findings suggest epigenetic modification of GPM6A and CHRNA9, both involved in calcium channel activity and development, may play a role in the pathophysiology of CVD under conditions of higher glycemic exposure in type 1 diabetes." (PMID 37533055, 2023).
tumor (14 papers, 2010 to 2026). "Among these genes, EFNA4 and TEDC2 were significantly upregulated, whereas CDC42EP2, STX11, THBD, TMEM88, and GPM6A were notably downregulated in tumor tissues compared with adjacent normal tissues." (PMID 42196266, 2026). "Current studies have shown that GPM6A does participate in tumor occurrence and development, but what role it plays and how it regulates are still not clear." (PMID 39957375, 2025). "HAND2, C2orf40, and GPM6A are hypermethylated and downregulated in tumor tissues, but low expression of all the three genes is related to significantly prolonged survival, and their upregulation results in poor prognosis of CRC patients." (PMID 39957375, 2025). "Blocking the expression of GPM6A with siRNA resulted in a significant reduction in cell invasion, indicating that GPM6A plays a role in the invasion of human tumor cells." (PMID 39957375, 2025). "Among these, we found some key genes previously reported to be involved in tumor invasion and progression in other types of tumors, such as GPM6A, ABAT, GFAP, and AQP4." (PMID 40575267, 2025). "The results of UALCAN analysis showed that lower GPM6A expression was positively correlated with cancer stage, tumor grade, nodal metastasis status, and histological subtypes in HCC." (PMID 35002514, 2022). "The xenograft results suggested that GPM6A upregulation delayed tumor growth and reduced tumor weight." (PMID 36405247, 2022). "This proves that GPM6A is involved in the invasion of human tumor cells." (PMID 39957375, 2025). "Apart from that, GPM6A is negatively correlated with tumor volume doubling time (TVDT)." (PMID 39957375, 2025). "Moreover, the tumor tissues from the xenograft mouse model were used to perform GPM6A IHC and WB assays." (PMID 35002514, 2022). "Our results are the first to demonstrate the involvement of GPM6A in human tumor cell invasion." (PMID 35883571, 2022). "Furthermore, GPM6A upregulation delayed tumor growth in nude mice subcutaneously injected with Lv-GPM6A or vector-transfected A549." (PMID 36405247, 2022). "In a non-tumor context, GPM6A is highly expressed in the CNS and its functions could be dependent on its interaction with laminin." (PMID 35883571, 2022). "However, GPM6A exhibits the characteristics of tumor suppressor genes in other malignant tumors." (PMID 39957375, 2025). "Xenograft results showed that GPM6A upregulation could delay tumor growth and reduce tumor weight." (PMID 39957375, 2025). "Within the 37-gene-set, we highlight GPM6A (Glycoprotein M6A), ABAT (4-Aminobutyrate Aminotransferase), GFAP (Glial Fibrillary Acidic Protein), and AQP4 (Aquaporin-4), known to play roles in tumor invasion and progression within various cancers." (PMID 40575267, 2025). "Using the same rationale, we selected three regulatory axes for tumor suppression; these axes are designated as ANXA2P1/miR-20b-5p/FAM241A (C4orf32), MIR99AHG/miR-218-5p/GPM6A, and SH3RF3-AS1/miR-34a-5p/HECW2." (PMID 36289596, 2022). "GPM6A was found to activate the Smad pathway in HCC cells, which serves as an important negative regulatory signaling pathway for the proliferation of epithelial cells, regulates tumor cell apoptosis and proliferation." (PMID 39957375, 2025).
cancer (8 papers, 2009 to 2025). A tumor composed of atypical neoplastic, often pleomorphic cells that invade other tissues. "Recent studies have shown the association of GPM6A with cancer." (PMID 36405247, 2022). "GPM6A induces the formation of filopodia, which is involved in the adhesion and migration of cancer cells." (PMID 39957375, 2025). "GPM6A activates Smad signaling pathway, and the role of this pathway in malignant tumors is ambiguous." (PMID 39957375, 2025). "Further understanding of the structure and function of its SNPs will help to better understand the relationship between GPM6A and various malignant tumors." (PMID 39957375, 2025). "In summary, the role of GPM6A is controversial not only in different types of malignant tumors, but also in the same type of malignant tumors." (PMID 39957375, 2025). "Further researches are needed to confirm and elaborate on the observed roles of GPM6A in various cancer processes and its potential as a prognostic indicator." (PMID 39957375, 2025). "More extensive studies are necessary to validate conclusions and to better understand the role of GPM6A in various cancers." (PMID 39957375, 2025). "Uncovering the underlying molecular mechanism of how GPM6A further affects the development and progression of malignant tumors by affecting EMT and filopodia will help elucidate the controversial role of GPM6A in malignant tumors." (PMID 39957375, 2025). "GPM6A expression in normal samples is significantly higher than that in malignant tumor samples, indicating that GPM6A is inhibited in malignant tumors." (PMID 39957375, 2025). "GPM6A is a neuronal membrane glycoprotein that has been detected in various cancers such as those of the colon, liver, and lungs." (PMID 38681779, 2023). "In the Human Protein Atlas Database, the RNA expression overview from The Cancer Genome Atlas shows an enrichment of GPM6A and GPM6B RNA in glioma." (PMID 35883571, 2022). "GPM6A mRNA expression was analysed in 33 types of cancers using The Cancer Genome Atlas (TCGA) datasets." (PMID 36405247, 2022). "WB analysis and IHC analysis showed that the GPM6A expression was much lower in cancer tissues than para-carcinoma tissues in HCC." (PMID 35002514, 2022). "qRT-PCR demonstrated circCCNB1/GPM6A underexpression and miR-106b-5p overexpression in cancer tissues compared to the para-carcinoma tissues in twenty HCC patients." (PMID 35002514, 2022). "In some malignant tumors, GPM6A shows cancer‐promoting properties." (PMID 39957375, 2025). "Researches have indicated that GPM6A is related to malignant tumors." (PMID 39957375, 2025). "GPM6A may make effect on the development of malignant tumors through influencing EMT and the formation of filopodia." (PMID 39957375, 2025). "Expressions and influences of GPM6A in various malignant tumors." (PMID 39957375, 2025). "On the one hand, GPM6A may have carcinogenic properties and is related to poor prognosis of malignant tumors." (PMID 39957375, 2025). "Its high correlation with GPM6A in GB and its involvement in the regulation of GPM6A expression reinforce the hypothesis of a pro-tumoral role of GPM6A in this cancer." (PMID 35883571, 2022). "Glycoprotein M6A (GPM6A) is a neuronal membrane glycoprotein reported to be related with cancer." (PMID 36405247, 2022). "Very few data are available on the involvement of GPM6A in cancers." (PMID 35883571, 2022). "As shown in the heatmaps, the hsa_circ_0001495, miR-125b-5p, and GPM6A were down-regulated in cancer tissues compared to their paired para-carcinomal tissues of HCC, whereas hsa_circ_0000688, miR-106b-5p, and four mRNAs (UNKL, GPRIN1, SMYD5, AURKB) were up-regulated." (PMID 35002514, 2022). "One recent report suggested that GPM6A might function as a chaperone in cancer cells as part of global profiling of the cell surface proteome for cancer cells." (PMID 19898621, 2009). "In addition, the role of GPM6A in certain malignant tumors needs further clarification." (PMID 39957375, 2025).
cancer (continued). "The GPM6A gene may serve as a clinical prognostic indicator in malignant tumors." (PMID 39957375, 2025). "These suggest that GPM6A may be an inhibitory factor for malignant tumors." (PMID 39957375, 2025). "These suggest that GPM6A may be a procancerous factor in malignant tumors." (PMID 39957375, 2025). "The expression of circCCNB1 and GPM6A were significantly down-regulated in HCC cells and cancer tissues, while miR-106b-5p expression was up-regulated." (PMID 35002514, 2022). "Nevertheless, GPM6A was found to activate the Smad pathway in HCC cells, while the Smad signaling pathway is a double‐edged sword for promoting and suppressing cancer in the treatment of malignant tumors." (PMID 39957375, 2025). "In summary, our results showed that the expression of circCCNB1 and GPM6A was significantly down-regulated in HCC cells and cancer tissues compared to the normal liver cells and para-carcinoma tissues, while the expression of miR-106b-5p was notably up-regulated." (PMID 35002514, 2022). "The role of GPM6A or PTPRZ1 in the radioresistance of GB or other cancer types has never been reported." (PMID 35883571, 2022). "However, the biological function of GPM6A in the occurrence and development of malignant tumors is not well understood." (PMID 39957375, 2025). "The role of GPM6A in cancer cells has not been extensively studied." (PMID 35883571, 2022).
GPM6A also shares sentences with these, for which no sentence is quoted: bipolar disorder (2 papers); mental disorder (2); neurological disorders (2); Obesity (2); Anorexia (1); anorexia nervosa (1); aortic valve calcification (1); autism (1); breast tumors (1); Cirrhosis (1); pancreatic tumor (1); protein misfolding disorders (1); thyroid tumor (1).